INS (insulin)
Diseases named in the same sentence as INS in open-access papers (continued):
Sharing a sentence is not in itself a finding about the gene and the disease.
Hypoglycemia (continued). "Inaccurate carbohydrate estimations that are used for calculation of prandial insulin are associated with high prevalence of postprandial hyper- and hypoglycemia, even with hybrid insulin delivery systems." (PMID 36914699, 2023). "Patients have also reported fears associated with insulin-related weight gain and accidental hypoglycemia, or low blood sugar, induced by an overproduction or excessive dosage of insulin." (PMID 36673730, 2023). "Insulin is a narrow therapeutic index medication and has been linked to hypoglycemia in up to 28% of patients." (PMID 36719713, 2023). "We confirmed that age, previous comorbidities (particularly, decreased glomerular filtration rate) and treatment during hospitalization with insulin or secretagogues are risk factors for hypoglycemia." (PMID 38044455, 2023). "These people at increased risk of hypoglycemia need near-physiologic insulin replacement to reduce exposure to hypoglycemia." (PMID 38089060, 2023). "In particular, insulin-independent processes affect BG levels mainly during PA, while insulin-dependent effects are the main cause for late-onset hypoglycemia and need to be considered for several hours post-PA." (PMID 36791144, 2023). "Insulin therapy is associated with weight gain and a greater risk of hypoglycaemia, both of which are associated with increased cardiovascular and other risks." (PMID 37152098, 2023). "Evidence suggests that intensive insulin regimens in patients with type 2 DM carry the highest risk for severe hypoglycemia, with nocturnal hypoglycemia episodes having a particularly high burden of risk." (PMID 36920464, 2023). "Therapy with basal insulin is recommended in view of its ease and convenience of initiation, flexible-dose titration regimens, and low risk of hypoglycemia, more so in patients with elevated fasting glucose." (PMID 36650625, 2023). "During the beginning of pregnancy, insulin secretion is physiologically elevated in the pancreatic β-cells, and this period can even be associated with states of hypoglycemia." (PMID 37239090, 2023). "Over the past few years, semi-closed-loop hybrid insulin pumps have been developed and are available for T1D patients, increasing flexibility and lowering the risk of hypoglycemia." (PMID 37705724, 2023). "Future studies should include information regarding the type of insulin, as long-lasting insulins have less risk of hypoglycemia." (PMID 37310947, 2023). "The illustrative case presented demonstrates this risk with severe hypoglycaemia and unconsciousness as a result, despite protection available to them from automated insulin delivery low and glucose suspend." (PMID 37864225, 2023). "Insulin antibody (IA) usually has low binding capacity and high affinity and rarely causes hypoglycemia, which is different from the high binding capacity and low affinity of IAA in IAS." (PMID 36844104, 2023). "Insulin secretion can be enhanced by sulphonylureas independently and therefore introduce diabetic patients to a heightened risk of hypoglycaemia." (PMID 37287751, 2023). "Insurance policies should also consider expanding CGM coverage to people using any insulin or oral medications with a higher risk of hypoglycemia (ie, sulfonylureas) and adults with physical, cognitive, or emotional barriers to finger sticks." (PMID 37463021, 2023). "The observation group had shorter time of blood glucose reaching the standard, smaller insulin dose, and lower risk of hypoglycemia than those of the control group (P<0.05)." (PMID 38223574, 2023). "Participants who are using glucose-lowering medications that have significant risk of hypoglycemia, such as insulin or sulfonylureas, will attend a video call prior to the start of classes with the study doctors." (PMID 37475033, 2023). "Anticipating resistance exercise in relation to aerobic training seems efficient to minimize the risk of hypoglycemia in individuals undergoing insulin therapy." (PMID 36593495, 2023).
Hypoglycemia (continued). "This is the first case documented of successful treatment with glucagon, anticonvulsants and intermittent mannitol for refractory hypoglycemia and seizure caused by fatal insulin overdose." (PMID 38026640, 2023). "Although in this study, CLC insulin delivery was seen to have decreased risk of AEs, hypoglycemia is still the dominant AE." (PMID 37574494, 2023). "In order to meet the daily insulin dose requirement of diabetic patients and avoid the risk of hypoglycemia caused by insulin overdose, an insulin-loaded modified SF MNs with both high dose and intelligent drug delivery effect was developed in this paper." (PMID 36810381, 2023). "The study participants' normal fasting tolerance and proper suppression of insulin secretion in response to hypoglycemia negate the possibility of an underlying insulin secretion problem." (PMID 37546099, 2023). "The Exercise Mode works on a target range of 140–160 mg/dL, allowing a reduced risk of hypoglycemia; when the predicted glucose value is <80 mg/dL the pump suspends the delivery of basal insulin." (PMID 36983941, 2023). "During pregnancy, only human insulin was widely used until recently, but its use is now limited due to the risk of hypoglycemia." (PMID 37775682, 2023). "To investigate effects of HNF1A loss on glucagon secretion during hypoglycemia, we performed i.p. insulin tolerance tests (IP-ITT)." (PMID 37943614, 2023). "The addition of a GLP-1 RA to basal insulin instead of using traditional prandial insulin is now increasingly chosen based on similar hemoglobin A1C (HbA1C) reduction and the additional benefits of weight loss and reduced risk of hypoglycemia." (PMID 37589043, 2023). "Because of the risk of hypoglycemia, insulin is an obvious medication that can be affected by fasting." (PMID 37383881, 2023). "In our meta-analysis, the infants born to mothers treated with insulin needed additional management for hypoglycemia, which is partly associated with an increase in NICU admission." (PMID 36593391, 2023). "Long-acting agents such as glargine and levemir are mostly administered at bedtime to cover basal insulin requirements and are associated with a lower incidence of hypoglycemia." (PMID 37298274, 2023). "There are several potential causes of hypoglycemia in diabetic patients, including improper insulin dosing, concurrent medications, or deteriorating renal and liver function, adrenal insufficiency." (PMID 38134112, 2023). "GLP-1 receptor agonists have several advantages over insulin sensitizers like TZDs, including weight loss, reduced risk of hypoglycemia, and possibly cardiovascular benefits." (PMID 38283440, 2023). "As far as SU and insulin are concerned, the risk of hypoglycemia should be carefully monitored in patients treated with these drugs, particularly in the elderly, in relation to a higher risk of falls and fractures." (PMID 38068310, 2023). "People with insulin-deficient diabetes who have impaired awareness of hypoglycemia have a more than six-fold higher risk of severe hypoglycemia and a 2-4-fold higher frequency of asymptomatic hypoglycemia than people with intact hypoglycemia awareness." (PMID 38089060, 2023). "Nonetheless, these studies were performed under intensive insulin therapy protocols, with demanding glucose targets, that also contributed for the risk of hypoglycaemia." (PMID 37173530, 2023). "In the present study, the time of blood glucose reaching the standard was shorter, the dose of insulin was smaller, and the risk of hypoglycemia after treatment was lower in the observation group." (PMID 38223574, 2023). "The main causes of postoperative hypoglycemia among diabetic patients during perioperative period include preoperative fasting, inappropriate insulin administration, and insufficient sugar supplementation." (PMID 37675290, 2023). "A similar reduction in the risk of global hypoglycemia was also seen in those who had experienced prior insulin management." (PMID 37185053, 2023).
Hypoglycemia (continued). "Under this circumstance, a potential benefit of a new insulin is sought in the safety data, i.e., reducing the risk of hypoglycemia." (PMID 38089060, 2023). "Discussion: The antidiabetic agents with the highest association of hypoglycemia found were pramlintide, insulin, acarbose, repaglinide, chlorpropamide, glyburide, exenatide, glimepiride, tolazamide, and lixisenatide." (PMID 37996825, 2023). "In hospitalized patients, in whom both hyperglycemia and hypoglycemia are associated with increased morbidity, mortality, and length of hospital stay, an insulin regimen is the preferred treatment." (PMID 37736430, 2023). "This study showed a significant association between insulin use and severe hypoglycemia (OR 2.257, p = 0.021)." (PMID 37758787, 2023). "Our study has shown that patients with coexisting T2D and COPD requiring insulin therapy was associated with a higher risk of hypoglycemia, hospitalization for COPD, bacterial pneumonia, and ventilator use." (PMID 37242426, 2023). "More aggressive basal rates, carbohydrate-to-insulin ratio, and Correction Factor were all associated with higher time in range 70–180 mg/dL, although also slightly increased hypoglycemia." (PMID 37751154, 2023). "Congenital hyperinsulinism (CHI) is a condition characterised by severe and recurrent hypoglycaemia in infants and young children caused by inappropriate insulin over-secretion." (PMID 38027197, 2023). "Congenital hyperinsulinism (CHI) is the most common cause of persistent hypoglycemia in infancy/childhood and is a serious condition associated with severe recurrent attacks of hypoglycemia due to dysregulated insulin secretion." (PMID 37056678, 2023). "Our multivariate analysis showed eGFR less than 60 mL/min/1.73 m2, history of previous event(s) of severe hypoglycemia, and insulin use were associated with increased severe hypoglycemia risk." (PMID 37758787, 2023). "CHI is a genetically and histologically heterogeneous disease marked by an inappropriately elevated level of insulin in the setting of underlying hypoglycemia." (PMID 36721237, 2023). "Since GLP-1 receptor agonists stimulate insulin release and inhibit glucagon secretion in a glucose-dependent fashion, there is a low risk of hypoglycaemia." (PMID 37209215, 2023). "In healthy subjects, insulin-induced hypoglycemia is associated with an increase in lipid peroxidation markers and ROS production." (PMID 37298308, 2023). "Despite its potential benefits for managing T1D, insulin therapy increases the risk of hypoglycemia with its potential cardiovascular risk factors." (PMID 36830610, 2023). "Are there any health risks associated with the planned hiking tour, especially for insulin-treated patients regarding possible occurrences of exercise-induced hypoglycemia?" (PMID 36674186, 2023). "Biochemical assessment identified hypoglycemia associated with suppressed insulin, c-peptide, and beta-hydroxybutyrate levels." (PMID 37909001, 2023). "GLP-1RAs have a low risk of hypoglycemia because their effects on insulin and glucagon secretion are glucose-dependent." (PMID 37456411, 2023). "Selecting the most cost-effective treatments with clinical evidence of the lower risk of hypoglycemia, especially newer insulin preparations, will provide the greatest likelihood of improving clinical outcomes and reducing the economic burden." (PMID 37046876, 2023). "This combination therapy shows the same efficacy as the basal bolus treatment regimen with respect to the glycemic control, but with a lower risk of hypoglycemia and weight gain, and is obtained with a lower dose of insulin." (PMID 36726134, 2023). "Course of disease, BMI, fasting C-peptide and creatinine are independent risk factors for hypoglycemia in T2DM patients after intensive insulin therapy." (PMID 38223574, 2023).
Hypoglycemia (continued). "These algorithms facilitate proactive modifications to insulin doses and lifestyle adjustments, thereby promoting improved glycemic control and mitigating the risk of hypoglycemia and hyperglycemia." (PMID 37724233, 2023). "The antidiabetic medications most commonly associated with hypoglycemia are insulin and insulin secretagogues." (PMID 37180737, 2023). "One example of this is the insulin which unit was originally defined as the amount of insulin required to cause convulsive hypoglycemia in a fasted 2 kg rabbit." (PMID 36679199, 2023). "This negative regulation of cortisol secretion can be observed, for example, in patients with insulinomas, where increased insulin causes a deficient cortisol response to hypoglycemia, whereas cortisol responses are normalized after their resection." (PMID 37718435, 2023). "The main disadvantage of insulin therapy is the parenteral route of administration and the risk of hypoglycaemia." (PMID 36837914, 2023). "Due to the relatively large number of insulin (27.5%) and sulfonylureas (35.3%) users in this study, drug changes were freely permitted to avoid hypoglycemia caused by IWT." (PMID 37200321, 2023). "β Cell–specific knockout of Lsd1 in mice led to dysregulated expression of these nutrient-responsive genes and most notably caused insulin hypersecretion resulting in hypoglycemia." (PMID 37066881, 2023). "It is possible that this disorder decreases instead the ability of the pancreas to dynamically regulate insulin secretion in response to noxious stimuli and thus only predisposes patients to hypoglycemia during illness or fasting." (PMID 37927489, 2023). "The glucose levels of six insulin-treated patients were measured using continuous glucose monitoring (CGM) devices, considering that insulin-treated patients can be at increased risk of exercise-induced hypoglycemia." (PMID 36674186, 2023). "At 14 d after intensive insulin therapy, the time of blood glucose reaching the standard was shorter, the dose of insulin was smaller, and the risk of hypoglycemia after treatment was lower in the observation group than those in the control group (P<0.05)." (PMID 38223574, 2023). "It regulates blood glucose via the incretin pathway, stimulating insulin and inhibiting glucagon secretion in a glucose-dependent manner, leading to lower blood glucose levels with low risk for hypoglycaemia." (PMID 37025414, 2023). "Insulin therapy, however, increases the risk of hypoglycemia, which is associated with adverse clinical outcomes." (PMID 37993898, 2023). "Insulin treatment increases the risk of hypoglycemia, which is associated with adverse effects on the central nervous system and higher risk of cardiovascular events and mortality, especially during a severe episode." (PMID 37293006, 2023). "We also showed that IDegLira added to metformin to simplify treatment maintains appropriate glycaemic control at least for 12 months with less hypoglycaemia and weight loss compared to the previous insulin regimens." (PMID 36461758, 2023). "Overall, reduced renal gluconeogenesis compromised metabolic pathways (including altered medication metabolism) and decreased insulin clearance are linked to a higher risk of hypoglycemia in patients with CKD." (PMID 36851310, 2023). "It is characterized by the hypersecretion of insulin, which causes severe hypoglycemia with possible neurological symptoms, such as seizures, confusion, blurred vision, and coma." (PMID 37103745, 2023). "Rapid-acting insulin analogues can then be added as needed, as they can rapidly lower blood glucose levels with less risk of postprandial hypoglycemia than regular short-acting insulin." (PMID 37242426, 2023). "Optimal glycaemic control is often limited by the risk of hypoglycaemia, and is made more challenging because insulin needs vary considerably day to day." (PMID 37289734, 2023).
Hypoglycemia (continued). "On the contrary, sulfonylureas, meglitinides, thiazolidinediones, and insulin therapies all increase the risk of hypoglycaemia and bodyweight gain." (PMID 37033652, 2023). "Mechanisms of weight gain from sulfonylureas include 1) hypoglycemia, which can induce increased caloric intake, and 2) increased insulin level, which can lead to lipogenesis and cause excess fat deposition." (PMID 38327904, 2023). "This is because of analog-insulin’s improved physiologic time-action profiles, a lower risk of developing hypoglycemia, and more flexible dosing." (PMID 36648847, 2023). "In type 2 DM, the risk of hypoglycemia is related to the duration of diabetes and the use of hypoglycemic agents, particularly insulin." (PMID 36920464, 2023). "While most AHAs carry a very low risk, especially when taken as indicated, insulins and insulin secretagogues carry a notable risk of hypoglycemia." (PMID 36789141, 2023). "The utilization of a data-driven approach enables the timely adjustment of insulin doses, resulting in the optimization of glycemic control and a reduction in the potential risk of hypoglycemia." (PMID 37724233, 2023). "When patients use sulfonylureas as medicine to control their type 2 DM, the risk of hypoglycemia needs to be considered, mainly because of the decreased clearance of insulin and oral hypoglycemic drugs and impaired renal gluconeogenesis." (PMID 38068443, 2023). "GI AEs were lower with the FRCs (compared to those receiving GLP-1RA); there was also a significant benefit in favor of FRCs in relation to weight loss and risk of hypoglycaemia (compared to those receiving insulin management)." (PMID 37185053, 2023). "Third, we didn't include the type of insulin used, as hypoglycemia risk is variable depending on insulin type." (PMID 37859676, 2023). "Diabetic patients who need insulin therapy or oral sulfonylureas and individuals at high cardiovascular risk should be given a treatment plan that minimizes the risk of hypoglycemia and its associated CVD risk factors." (PMID 36830610, 2023). "The causes of the delay in adjusting insulin titration are complex and include concerns from subjects, such as fear of hypoglycemia and weight gain." (PMID 37835008, 2023). "Though there is no statistical significance between the two, GLP1-RAs carry a significantly lower risk of hypoglycemia and have been shown to induce weight loss, while insulin possesses a higher risk of hypoglycemia, often causing unintentional weight gain." (PMID 37090383, 2023). "It has been shown that endogenous ligands or synthetic agonists control the release of insulin in a glucose-dependent way, contrary to insulin, sulfonylureas, and other widely used drugs, having minimal risk of hypoglycemia or other side effects." (PMID 38004168, 2023). "This secretion is not properly regulated by glucose, and as a result Insulinomas continuously and inappropriately secrete insulin causing hypoglycaemia." (PMID 36950054, 2023). "Hypoglycemia occurred in 154 (47.5%) patients during their hospitalization and was associated with advanced age, previous insulin therapy, higher Charlson Comorbidity Index, lower body mass index and lower baseline HbA1c values." (PMID 38044455, 2023). "Intensive insulin therapy is the standard of care to control BG but is associated with unacceptable rates of hypoglycaemia and metabolic crisis." (PMID 38571572, 2023). "Alternatively, disrupted first phase in insulin secretion has been proposed as a plausible mechanism underlying post-prandial hypoglycemia." (PMID 37726785, 2023). "In conclusion, history of previous severe hypoglycemia, eGFR less than 60 mL/min/1.73m2, and insulin use were associated with severe hypoglycemia." (PMID 37758787, 2023). "The treatment regimen with vildagliptin along with insulin (VIL-INS) for 24 months was safe and effective in reducing glycated hemoglobin (HbA1c) levels, the dose and frequency of insulin injections, and the risk of hypoglycemia in patients with T2DM." (PMID 38021574, 2023).